FGFR1 (fibroblast growth factor receptor 1)
Diseases named in the same sentence as FGFR1 in open-access papers (continued):
Sharing a sentence is not in itself a finding about the gene and the disease.
breast cancer (continued). "It is important to note that breast cancer cells also use the Jagged1/Notch pathway to promote bone metastases, thus a focus on FGFR-1 expression in breast cancer bone metastases could unveil new answers in drug resistance mechanisms." (PMID 37182144, 2023). "Abnormal FGFR1 activation plays an important role in the regulation of breast cancer metastasis." (PMID 37490511, 2023). "Fibroblast growth factor receptor 1 (FGFR1) amplification is associated with breast cancer development and aberrant FGF signaling found in the biological processes related to both high mammographic density and breast cancer microenvironment." (PMID 37546410, 2023). "FGFR1 has been reported to enhance the expression of vascular endothelial growth factor A through tumor necrosis factor alpha‐induced protein 3, thus contributing to breast cancer angiogenesis." (PMID 37750089, 2023). "Although FGFR1 is amplified more often in breast cancer, both FGFR1 and FGFR2 amplified and overexpressing breast cancers could likewise benefit from AZD4547 treatment." (PMID 37805590, 2023). "Nuclear FGFR1 is also present in breast cancer where it can promote breast cancer cell invasion." (PMID 36357571, 2023). "Indeed, FGFRs contribute to cyclin-dependent kinase 4/6 inhibitor (CDK4/6i) resistance and FGFR1 overexpression reduced the efficacy of CDK4/6i treatment for breast cancer patients enrolled in the MONALEESA-2 study." (PMID 37715207, 2023). "Notably, FGFR1 gene amplification has been observed in metastatic lobular breast cancer, ER+ breast cancer, and HER2− breast cancer." (PMID 38077251, 2023). "Previously, a higher rate of FGFR1 amplification was reported in invasive breast carcinoma relative to ductal carcinoma in situ, particularly in high grade tumors with FGFR1 amplification present in up to 14% of breast cancer patients." (PMID 37546410, 2023). "The various FGFR inhibitors in development, taken together with our findings on FGFR1/2/3 acquired alterations in LBx, might be suggestive of patients with relapsed ER+ breast cancer being an appropriate population for targeted enrollment." (PMID 36470901, 2022). "An interesting possibility is that FGFRL1 could also in the nucleus act via FGFR1, which has been reported to have nuclear functions in breast cancer." (PMID 35053442, 2022). "The copy number of 4EBP1 and FGFR1 showed a strong correlation in breast cancer." (PMID 35626002, 2022). "In addition to the FGF3 locus (int-2 in mice), high-throughput analysis of the MMTV insertional mutagenesis identified an activated FGF pathway in 67% of the mammary tumors with virus common insertion sites near FGFR1 and FGFR2." (PMID 35996584, 2022). "FGFs activating FGFR1 have the capacity to increase the differentiation of osteoclast; therefore it has been suggested that this would increase FGFR1-dependent migration of breast cancer cells towards the bones, one of the known metastatic sites in breast cancer patients." (PMID 35193394, 2022). "FGFR1 signalling may promote perturbations of the breast cancer microenvironment and immune response which might lead to the formation of metastasis." (PMID 35193394, 2022). "Interestingly, resistance to the CDK4/6 inhibitor ribociclib, in combination with fulvestrant in ER+ breast cancer, can be mediated by amplification of FGFR1." (PMID 36231142, 2022). "Furthermore, breast cancer samples were grouped according to FGFR1 expression in a single-cell dataset (GSE114727), and it also showed that the group with high FGFR1 expression had more fibroblasts and less CD8+ T cell infiltration in TME." (PMID 35832090, 2022).
breast cancer (continued). "A further tumour agnostic basket trial, denoted FUZE (NCT03834220) is currently assessing objective response rate to Debio-1347 in biliary, urothelial and solid cancers (including breast cancers) with FGFR1–3 fusions or rearrangements, based on encouraging phase 1 data." (PMID 35193394, 2022). "FGFR1 amplification is correlated with lower overall survival in HR+ breast cancer." (PMID 33947144, 2021). "Since highly mesenchymal TNBCs are associated with elevated expression of both FGFR1 and HGF, we assessed whether these two genes in combination could predict outcome in breast cancer patients." (PMID 33772015, 2021). "Besides, the positive gene of fibroblast growth factor receptor 1 (FGFR1) is also correlated to breast cancer resistance." (PMID 34651424, 2021). "Finally, the prognostic power of HGF and FGFR1 co-expression in basal breast cancers offers a new strategy for stratifying patients, as well as potential anti-TIC therapeutic targets that warrant further investigation." (PMID 33772015, 2021). "Finally, we find that human TNBCs with mesenchymal characteristics are significantly enriched for HGF and FGFR1, and that co-expression predicts poor prognosis among basal breast cancer patients." (PMID 33772015, 2021). "In addition, inhibition of FGFR1 has been shown to enhance the immune checkpoint inhibitor response in breast cancer." (PMID 35068946, 2021). "Importantly, basal breast cancers that display elevated MET and FGFR1 signatures are associated with poor relapse-free survival." (PMID 33772015, 2021). "Consistent with our genomic comparison between primary and metastasis, the ESR1 mutation is found by the mean SHAP value as the most predictive feature of metastatic breast cancer, followed by FGFR4 mutation, SOX2 amplification, ERBB2 mutation, and FGFR1 mutation." (PMID 34795255, 2021). "Our results advance in the task of finding a therapeutic scenario and a patient sub-population where FGFR inhibitors would deserve clinical investigation: HR+ breast cancer patients with amplification and/or overexpression of FGFR1 upon progression to aromatase inhibitors." (PMID 33579347, 2021). "A previous study showed that combination of palbociclib with ER-targeting fulvestrant and FGFR-targeting Lucitanib resulted in enhanced inhibition of FGFR1-overexpressing breast cancer cells, but the response of ER signaling in the treated cells was not thoroughly analyzed." (PMID 34831231, 2021). "Overexpression of FGFR1 may contribute the poor prognosis of ERα-positive breast cancers and drive anchorage-independent proliferation and endocrine therapy resistance." (PMID 34645792, 2021). "For instance, FGFR1 upregulation leads to endocrine therapy resistance in breast cancer patients." (PMID 34722544, 2021). "Furthermore, breast cancer cell line (MDA-MB-231) was used to investigate the probable association of FGFR1 with SHH and GLI1 in breast cancer progression." (PMID 34722544, 2021). "FGFR1 is amplified or overexpressed in 15% of ER+ breast cancers." (PMID 34830174, 2021). "Similarly, FGFR1 alternative FGFR1α/FGFR1β splicing was found to play a key role in breast cancer and FGFR3 splicing promoted aggressiveness in prostate cancer." (PMID 34830836, 2021). "Furthermore, the effect of FGFR1–SHH pathway signaling on the motility of breast cancer cells was evaluated using wound-healing assay." (PMID 34722544, 2021). "FGFR1 is a proven transcriptional target of FOXC1 in breast cancer." (PMID 34540690, 2021). "For example, FGFR1 expression was identified as a predictor of poor overall survival in TNBC patients, and FGFR1 amplifications and overexpression have also been linked to de novo tamoxifen-resistance in luminal type breast cancer cell lines." (PMID 33916323, 2021). "Interestingly, 5 out of 16 SHH pathway genes showed core enrichment in FGFR1-expressed breast cancer patients using leading-edge subset method." (PMID 34722544, 2021).
breast cancer (continued). "The heatmaps of the 10 HR−/HER2+ breast cancers were homogeneous, while for 9 HR-/HER2− cases, a major cluster with ATM, FGFR1, and WT1 frameshift mutations (n = 6 for ATM1, FGFR1 and n = 5 for WT1) and a minor one with JAK3 splice site mutations were prominent (n = 3)." (PMID 34203389, 2021). "The genetic aberrations in FGFR1 were first documented in breast cancer." (PMID 34722544, 2021). "Likewise, FGFR1 has been found to be co-amplified with the CCND1 gene towards poor outcomes in estrogen-receptor (ER)+ breast cancer." (PMID 33081025, 2020). "Associations between leptin mRNA and FGFR1 mRNA expression are positive in breast tumor-adjacent tissue (Rho = 0.26) and primary breast cancer tissue (Rho = 0.16), and negative in normal breast tissue (Rho = −0.27)." (PMID 33019728, 2020). "Further investigations have to show whether the copy number gain of the gene lead to increased expression of this growth factor receptor in our breast cancer cohort and whether FGFR1 overexpression might predict prognosis." (PMID 32852708, 2020). "A total of 894 patients with breast cancer were initially included in the FGFR1 analysis." (PMID 32852708, 2020). "Together, these results indicate that the amplification of FGFR1 may represent an oncogenic driver contributing to breast cancer progression." (PMID 33081025, 2020). "In addition, estrogen deprivation led to an increased expression of FGFR1 and FGF ligands in ER+/FGFR1-amplified primary tumors and breast cancer cells." (PMID 33081025, 2020). "Amplification of FGFR1 is found in several types of cancer (e.g., nonsmall cell lung carcinoma, head and neck tumors, breast cancer, ovarian cancer, bladder cancer, and rhabdomyosarcoma), with a frequency of up to 10% in breast cancer." (PMID 32852708, 2020). "This is in line with the evidences proving the oncogenic role of FGFR1 in breast cancer." (PMID 32188012, 2020). "Moreover the combination of CDK4/6 inhibitor palbociclib and FDA-approved FGFR inhibitor erdafitinib showed a complete in vivo response in SCID/beige mice xenografted with estrogen receptor positive and FGFR1 amplified breast cancers." (PMID 32188012, 2020). "FGFR1 and Jak2 have both been observed to be upregulated in breast cancer." (PMID 33019728, 2020). "Therefore, Jak2 is a potential therapeutic target for FGFR1 amplified breast cancer, especially in the context of obesity." (PMID 33019728, 2020). "The genomic analysis of The Cancer Genome Atlas (TCGA) and the Molecular Taxonomy of Breast Cancer International Consortium (METABRIC) databases has confirmed that the amplification of FGFR1 is the highest among the FGFR family members, as it occurs in nearly 14% of breast cancer patients." (PMID 33081025, 2020). "It is worth mentioning that the amplification of FGFR1 has been correlated with aberrant ligand-dependent and ligand-independent signaling, which may lead to resistance to endocrine treatments in breast cancer." (PMID 33081025, 2020). "In addition, patients with ER+ metastatic breast cancer displayed the amplification of FGFR1 in circulating tumor DNA (ctDNA), hence mirroring the findings obtained in genomic studies of ER+ breast cancer tissues." (PMID 33081025, 2020). "This mutation is predicted to be deleterious, possibly activating this uncommon driver of breast cancer and may have contributed, in concert with FGFR1 gain, to the clonal expansion observed in this patient." (PMID 33208147, 2020). "Moreover, the up-regulation and secretion of FGF2 toward the stimulation of FGFR1 signaling in breast cancers was reported to occur upon estrogen stimulation through the classical ER." (PMID 30866584, 2019).
breast cancer (continued). "Therefore, we were interested in inspecting estrogen regulation of FGFR1 splicing and its consequence in breast cancer cells." (PMID 30713601, 2019). "As FGFR1 as well as FGFR2 are expressed in about 10% of breast cancers, these have gained attention for several purposes, including targeting newer treatments against these factors and using these as determinants of prognosis and overall survival of the patients." (PMID 31754359, 2019). "Next, we examined the expression of FGFR1 isoforms in three breast cancer subtypes." (PMID 30713601, 2019). "Deregulation of FGFR signaling by genetic alterations of FGFR1 has been found in breast cancer." (PMID 30713601, 2019). "As a molecular target, we have chosen FGFR1, since it can regulate tumor growth and stimulate angiogenesis, either by aberrant signaling or by overexpression on the cancer cell surface, as reported for multiple lung and breast cancers." (PMID 30968602, 2019). "Therefore, in order to assess the functional FGF2/FGFR1 interplay between CAFs and breast cancer cells, we generated the FGFR1-knockout MDA-MB-231 cells using CRISPR/Cas9 genome editing strategy." (PMID 30866584, 2019). "About one-fourth of breast cancers potentially expressed FGFR1 amplification." (PMID 31754359, 2019). "Similarly, no objective responses (0/31) were observed in a phase I study of infigratinib in breast cancer (FGFR1/2, amplified n = 25)." (PMID 35582593, 2019). "FGFR1 signalling was shown to suppress PR expression in vitro and this was confirmed by demonstration of an inverse correlation between FGFR1 and PR in human breast cancer tissue." (PMID 31142340, 2019). "In accordance with these observations, a large-scale genomic analysis of METABRIC and TCGA databases allowed us to assess not only that FGFR1 represents the most amplified receptor of the FGFRs family members but also that FGFR1 amplification occurs in nearly 14% of breast cancer patients." (PMID 30866584, 2019). "Amplification of FGFR1 located in chromosome 8p11-12 in 10-15% of breast cancer, has been correlated with FGFR1 overexpression and poor overall survival, particularly in estrogen receptor-positive (ER+) breast cancer." (PMID 30713601, 2019). "Of note, we were unable to identify any ER+/HER2−/FGFR1-amplified breast cancer cells without associated CCND1 amplification." (PMID 30914635, 2019). "Upon FGF2/FGFR1 activation, breast cancer cells may acquire invasive phenotype features modulating the expression of cell junction proteins, promoting a spindle-like morphology and increasing cell motility." (PMID 30866584, 2019). "The FGFR-specific inhibitors NPV-BGJ398, AZD4547 and JNJ-42756493 are under development for treating lung and breast cancers with FGFR1 amplification, gastric cancer with FGFR2 amplification, cholangiocarcinomas with an FGFR2 fusion, and urothelial cancers with FGFR3 alterations." (PMID 31601997, 2019). "Finally, in breast cancer cells, α3-integrin has been reported to physically disrupt the interaction between FGFR1 and E-cadherin, increasing the metastatic process." (PMID 30909436, 2019). "A similar mechanism was observed for FGFR1 in breast cancer cells." (PMID 30577533, 2018). "Furthermore, amplification and overexpression of FGFR1 contributes to poor prognosis in luminal type breast cancers and serve as an independent predictor of poor outcome." (PMID 30359238, 2018). "Moreover, elevation of FGFR regulates tumor stroma remodelling and tumor recurrence in FGFR1-driven breast cancer." (PMID 29455658, 2018). "The increased level of FGFR1 is observed in up to 15% of human breast cancers, especially in more invasive breast cancers, and may be one of the oncogenic drivers." (PMID 30577533, 2018). "Breast cancer cells contain FGFR1 truncation, which resides in the nucleus." (PMID 30577533, 2018). "In addition to ER+ breast cancer, amplification of FGFR1 gene correlated with poor prognosis in HER2- breast cancer." (PMID 29455658, 2018).
breast cancer (continued). "Alternatively, FGFR1 activation may also work with mutant Ras to promote breast cancer cell proliferation and progression via its other signaling pathways that do not use Ras and ERK1/2." (PMID 30111373, 2018). "Importantly, the frequency of these genetic aberrations of FGFR1 was found to be particularly high in breast cancers, which reached 18% of the breast tumor samples examined." (PMID 30111373, 2018). "Based on the results that osteoclasts express FGFR1 during osteoclastogenesis, further studies were performed to determine whether conditioned medium collected from breast cancer cells was capable of activating FGFR-induced signaling pathways in osteoclasts." (PMID 28968431, 2017). "Amplification of the chromosomal region 8p11-12, the genomic location of FGFR1, has been detected in 10% of breast cancers (predominantly in estrogen receptor (ER) positive cancers) and this finding has been related to higher FGFR1 expression levels correlating to worse prognosis." (PMID 28030802, 2017). "Previous studies have reported FGFR1 overexpression and amplification in breast cancer." (PMID 28125801, 2017). "FGFR1 amplification was observed in all four subtypes of breast cancer." (PMID 28125801, 2017). "Finally, in patients with breast cancer dovitinib showed more antitumor activity in tumors with high levels of FGFR1 amplification." (PMID 28980224, 2017). "To further confirm the ability of FGFR signaling to drive resistance to ErbB inhibition we analyzed the CCLE database by comparing the documented IC50 values for Lapatinib and the corresponding expression levels of the FGFR1 in 27 analyzed breast cancer cell lines." (PMID 27825137, 2016). "Furthermore, our utilization of both the HMLE and BT474 models of Her2+ breast cancer clearly demonstrate that enhanced FGFR1 expression when in the presence of FGF ligand is sufficient to facilitate resistance to Lapatinib treatment." (PMID 27825137, 2016). "Therefore, this study was designed to investigate FGFR1 protein expression in a large cohort of breast cancers by IHC staining." (PMID 26673008, 2016). "The relationship of FGFR1 expression with multiple relevant clinicopathologic features, tumor biomarker panels as well as the prognostic value in different molecular subtypes of breast cancer was investigated." (PMID 26673008, 2016). "In breast cancers, FGFR1 is mainly localized in the cytoplasm and cell membrane." (PMID 26673008, 2016). "FGFR1 was the first reported oncogene in the 8p11 region, and its amplification and overexpression has been related to poor prognosis and endocrine resistance in breast cancer." (PMID 25596748, 2015). "The FGFR1 drives stronger downstream pathway activation than other FGFRs, and its amplification has been verified as independent prognostic factor in some cancers including breast cancer." (PMID 26788508, 2015). "In addition, the importance of EGFR signaling in tumor dormancy and recurrence of FGFR1-driven mammary tumors provides a further rationale for combinatorial treatments in breast cancers harboring FGFR1 amplification." (PMID 26581390, 2015). "However, in certain breast cancer cell lines, silencing Fgfr2 with siRNA results in increased Fgfr1 levels, providing a precedent for our observations." (PMID 24824078, 2014). "MCF7 (breast cancer) cells were used as a positive control for FGFR1 expression." (PMID 24503018, 2014). "Also, BreastMark identifies FGFR1 as a marker in the basal subtype of breast cancer, which has been previously shown as a marker of poor prognosis in the luminal subtypes." (PMID 23820017, 2013). "FGFR1 has been described as being amplified in 10% of breast cancers." (PMID 23483937, 2013). "Furthermore, we showed that FGFR1 amplification is most frequently found in the luminal B subtype among the various breast cancer subtypes." (PMID 22863309, 2012).